CD4 (CD4 molecule)
Diseases named in the same sentence as CD4 in open-access papers (continued):
Sharing a sentence is not in itself a finding about the gene and the disease.
tumor (continued). "The anti-tumor effect conferred by B cell deficiency in all three models was associated with increased T cell and NK cell infiltration and more vigorous Th1 cytokine and cytolytic T cell responses, and in EMT-6 was also associated with decreased proliferation of CD4+FoxP3+ Tregs." (PMID 27437104, 2016). "As a result, infiltrated Tregs can exert suppressive effects on effector CD8+ and CD4+ T cells either through direct cell-to-cell contact or indirectly by generating interleukin-10 (IL-10) and transforming growth factor β (TGFβ) in situ, which helps tumor cells to evade the immune system." (PMID 27389040, 2016). "CD4+ T cell priming in the presence of B cells has been reported to drive the response towards a Th2 phenotype, which may in turn reduce the effectiveness of T cell-dependent tumor control." (PMID 27121060, 2016). "In addition, extensive studies have focused on IC expression and function of CD8+ T cells with less known regarding IC expression on CD4+ T cells; and while CD8+ T cells are major drivers of viral and tumor clearance, CD4+ T cell help plays a major role in these responses." (PMID 27379090, 2016). "Thus, our findings suggest that CXCL14, secreted by epithelial cells, might be one of the key regulators for NK, CD4+ T, and CD8+ T cells to drive tumor clearance during HPV-associated cancer progression." (PMID 27143385, 2016). "Moreover, CD4+ T cells can directly or indirectly lyse tumor cells." (PMID 27368058, 2016). "In this report, the patient had a complete response even though only one antigen was targeted and only 50%–75% of the tumor expressed this antigen; leading to the thought that CD4+ T-cells may play a greater role in coordinating an immune response resulting in antigen or epitope spreading." (PMID 27657129, 2016). "Further to that, anti-tumor activity has not yet been demonstrated in an MDV resistance model independent of genetic factors that predispose resistance to neoplastic transformation of CD4+ T cells." (PMID 27894330, 2016). "Furthermore, our flow cytometric analysis of the infiltrate at the human endpoint of the experiment showed that T cells are more abundant in the infiltrate in non-irradiated tumours (CD4+ 14 ±11%; CD8+ 19 ±14%) as compared to irradiated tumours (CD4+ 5 ±2%; CD8+ 8 ±11%)." (PMID 27427766, 2016). "More detailed sub-type level characterization of the CD4+ cell infiltrates is needed to define the biological and clinical significance of this trend: the T helper (Th) 1 and Th2 subsets have opposite effects on tumor growth, and Th1:Th2 ratios can change radically during tumor progression." (PMID 27441558, 2016). "Therefore, fusions of autologous DCs and autologous tumor cells may be more effective in targeting tumor cells because they can stimulate antigen-specific CD4+ T cells." (PMID 27240347, 2016). "However, the proportion of Tregs within the tumor-associated CD4+ population did not change with TMZ treatment." (PMID 26829221, 2016). "Further, the frequency of CD4+ T lymphocytes expressing the transcription factor FoxP3, a marker of regulatory T cells (Treg), did not significantly change in the tumor microenvironment or in the spleen, but modesty increased in the blood of tumor-bearing mice." (PMID 27936099, 2016). "CD4+ T cells might contribute significantly to tumor control by tumor antigen recognition via MHC class II on the tumor cells or indirectly by providing T cell help to CD8+ T cells after being activated by antigen-presenting cells presenting released tumor antigens in MHC class II." (PMID 27060000, 2016). "Moreover, a significant reduction in the number of CD4+ and CD8+ TILs with the development of NDs in more advanced tumors may be associated with lower tumor immunogenicity, resulting in immune tolerance towards tumor tissue." (PMID 26927070, 2016).
tumor (continued). "Interestingly, the frequency of intratumoral CD4+IFNγ+ T cells significantly correlated with that of intratumoral CD8+IFNγ+ T lymphocytes as well as of intratumoral CD4+IL17+ T cells in both types of tumor, suggesting their coordinated homing to the tumor site." (PMID 26824503, 2016). "Thus, in addition to stimulating CD8+ cellular and antibody-mediated immune responses, SurVaxM may provide important tumor-specific CD4+ helper support." (PMID 27576783, 2016). "It should be noted that increased CD4 to CD8 T cell ratio may be indicative of a Th2 type immune response at the tumor site, which may promote an immune tolerance state; however, greater CD8 T cell activation in the tumors from mice maintained on a KD suggests this is not the case." (PMID 27178315, 2016). "As CD4+ effector cells are not commonly the cytotoxic effector cells in an immune response, we hypothesized that the combination treatment induced M1 polarization of mononuclear cells in the tumor microenvironment, potentially recruited by IFNγ-secreting CD4+ cells." (PMID 27190629, 2016). "The exception constituted by CD4+ Treg, whose intratumoral frequency was greater than that of the apparently free-of-tumor tissue, may reflect the need for a critical size in order the tumor could efficiently generate/recruit Treg." (PMID 26824503, 2016). "It indicated that CD44 expression may regulate anti-tumor immunity by suppressing CD4 expression." (PMID 27323782, 2016). "Thus, enhanced infiltration of CD8+ and CD4+ effector T cells in tumors and altered balance between effector T cells and regulatory T cells in favor of immunity contributed to the augmented efficacy of IL-21 and IL-7 co-expressing tumor cell vaccine." (PMID 27571893, 2016). "Therefore, the ability of TR-CD4 to directly recognize cancer cells is especially important for the provision of CD4-help in the tumor microenvironment and may thereby lead to durable anti-tumor responses." (PMID 26447332, 2015). "Therefore, this study maybe suggested that in the late tumor stage, CD4+ T cells become more important for promoting tumor growth." (PMID 26587366, 2015). "To determine whether CXCR3 was required for intra-tumoural recruitment of CD4+ T cells we tested whether CXCR3-desensitization through pre-incubation with CXCL10 would interfere with the ability of adoptively transferred T cells to access the tumour." (PMID 25495686, 2015). "Therefore, the identification of MHC class II-restricted tumor antigens, which can stimulate CD4+ T cells, may provide opportunities for developing effective cancer vaccines." (PMID 25993655, 2015). "Therefore, identification of tumor antigens recognized by CD4+ T cells may be beneficial to the development of successful vaccination strategies." (PMID 25993655, 2015). "Since a strong TA-CIN-specific CD4+ T cell response was observed after vaccination of naïve BALB/c mice with TA-CIN/GPI-0100, we examined whether this TA-CIN-specific CD4+ T cell response was also induced in TC-1 tumor-bearing C57BL/6 mice after vaccination using both fresh and frozen vaccine." (PMID 25560237, 2015). "Therefore, it seems that the presence of a high number of tumor cells in the lymph node may diminish CD4+ cells." (PMID 25605488, 2015). "In addition, absolute Foxp3+ Treg cell numbers revealed a rapid increase compared with that of the other T cell subsets in the tumor sites, further confirming that Treg cells are the most dominant CD4+ T cell subset forming a tumor suppressive microenvironment at late stage of tumor progression." (PMID 25968569, 2015). "However, in the late cancer stage, CD4+ TILs significantly increased in numbers and its dominant subsets changed to Treg and Th17 cells, which may contribute to tumor promotion." (PMID 25968569, 2015). "Indeed, some CD4 Th1 cells have also direct tumor-recognizing ability." (PMID 26350591, 2015).
tumor (continued). "In addition, we observed that CD4+ T cell subsets have distinct distributions in peripheral organs (blood, spleen and lymph nodes), as in tumor sites, further indicating that immune profiles in peripheral organs cannot predict immune subsets in situ within the tumor microenvironment." (PMID 25968569, 2015). "Therefore, our studies suggested that in the late tumor stage, CD4+ T cells may become more important for promoting tumor growth." (PMID 25968569, 2015). "Finally, MDSCs contribute to an immunosuppressive TME by inducing the development of Tregs in tumor-bearing mice, as adoptive transfer of MDSCs and CD4+ T cells in MCA26 colon carcinoma cell line-bearing irradiated mice, induces expression of FOXP3 in transferred T cells." (PMID 26500653, 2015). "Notably, there were about 15% of tumor-infiltrating CD4+ T cells expressing IFNγ in WT mice whereas there were only 9% of them in KO mice, suggesting that AMPK deficiency may impair IFNγ production in tumors." (PMID 25760243, 2015). "Thus, traditional vaccine approaches relying on soluble protein or peptide tumor antigens may skew immune responses to CD4+ T cell responses, while failing to induce sufficient CTL responses." (PMID 26350600, 2015). "In order to determine whether gal epitope expression on vaccinated cells could activate CD8+ T cells, which become Cytotoxic T cells and destroy tumor cells, or activated CD4+ T cells, which help tumor-specific B cells to produce antitumor antibodies, we performed flow cytometry analysis." (PMID 26673159, 2015). "Inthis study, we found that intratumoral injection of λ-carrageenan couldinhibit tumor growth in B16-F10 and 4T1 bearing mice and enhance tumor immuneresponse by increasing the number of tumor-infiltrating M1 macrophages, DCs and moreactivated CD4+CD8+ T lymphocytes in spleen." (PMID 26098663, 2015). "Although IL-6 did not diminish or promote in vivo expansion of CD4+ T cells in response to vaccination, the age-associated increase in IL-6 dampened Th1 differentiation of CD4+ T cells and subsequent induction of tumour-specific CD8+ T cells, and thereby promoted cancer progression in aged mice." (PMID 25850032, 2015). "TCR clonotypes are largely distinct between Foxp3− and Foxp3+ CD4+ tumor-infiltrating T cell sub-populations, indicating that conversion does not account for intra-tumoral Treg-enrichment and supporting the hypothesis that Tregs within the tumor are thymus-derived Tregs (tTregs)." (PMID 26433463, 2015). "In addition, IHC staining of tumor biopsies confirmed the expression of CD22 in CD4+ T cells." (PMID 25957418, 2015). "Indeed, the association between improved HER2369–377-specific CD8+ T-cell immune responses and tumor eradication in pCR patients may reflect the ready availability of CD4+ T cell help." (PMID 25997452, 2015). "We observed that the proportion and relative cell numbers of CD4+IL-17+ subset dramatically went up at the early stage and reached a peak at the middle cancer stage, and then significantly dropped down at the late stage of tumor progression in both 4T1 and E0771 tumor models." (PMID 25968569, 2015). "Despite the inefficient ability of CD4+ T cells to directly recognize target cells expressing intracellular proteins such as tumor antigen-expressing cancer cells, a growing body of evidence indicate that tumor antigen-specific CD4+ T cells play a pivotal role in orchestrating tumor eradication." (PMID 26447332, 2015). "Therefore, the identification of MHC class II-restricted tumor antigens capable of stimulating CD4+ T cells may provide opportunities for developing effective cancer vaccines." (PMID 25993655, 2015). "However, reductions in the proportions of CD8α+CD4- DCs extend beyond the tumor." (PMID 25886502, 2015).
tumor (continued). "We then sought to examine whether CD4+CD25-CD69+ T cells were directly responsible for relapse or if the presence of a tumor induced the increase in this subset of T cells, which led us to the following question: what is the biological role of CD4+CD25-CD69+ T cells during allo-HSCT?" (PMID 24984576, 2014). "Furthermore, depletion of CD4 T cells during vaccination produced complete tumor eradication and established immunological memory that could protect against subsequent tumor growth." (PMID 25186961, 2014). "Thus, the nature of the antigen, by virtue of its cellular localization and accessibility to APCs, might determine the ability of the antigen to serve as an efficient tumor-specific antigen in CD4+ T cell responses." (PMID 24782871, 2014). "These actions are driven through MHC class II antigen presentation, and we observed here that MHC class II-deficient, but not MHC class I-deficient mice, cannot eradicate the tumor, which is further indication of the involvement of the CD4+ rather than the CD8+ T-cell subset." (PMID 24830315, 2014). "Furthermore, the average numbers of CD8-positive T cells in tumor parenchyma and tumor stroma were significantly increased, compared with the numbers of CD4-positive cells (CD8 versus CD4: tumor parenchyma, 16±2.5 versus 7.4±0.9, P<0.01; tumor stroma, 32.8±4.2 versus 22±3.6, P<0.05)." (PMID 25289108, 2014). "Furthermore, the observation that selective CD4+ TH cell silencing may abrogate the anti-tumor response points to the CD4+ TH cells as crucial." (PMID 25629004, 2014). "Despite the late onset of the immunotherapy also after vaccination alone improved infiltration of CD8+ T cells (fold change 1.4) and CD4+ T cells (fold change 0.6) could be observed suggesting beneficial effects of the immunotherapy even with the high tumor burden." (PMID 25127546, 2014). "Finally, the failure of RES to enhance αOX40-mediated tumor free survival in aged mice compared to aged control mice could be due in part to the inability of RES to maintain effective CD4 T cell priming." (PMID 24682539, 2014). "Therefore, the negative association between CXCL17 and CD4 cells also indicated the pro-tumor effect of CXCL17 in HCC." (PMID 25303284, 2014). "In the IL-18 and TK/GCV combination gene therapy group, infiltration of CD4+ T cells at the injection site of IL18-TK52 cells indicated that the local pre-treatment of IL-18 might maintain the T-lymphocyte status around the tumor." (PMID 25051201, 2014). "Furthermore, TGF-β secreted by Bregs could convert CD4+ T cells into Tregs that would promote tumor progression." (PMID 24991577, 2014). "In addition, the observed tumor-promoting propensity of some CD4+ T cells may have implications for adoptive T-cell therapy in general." (PMID 24853673, 2014). "Additionally, tumor protection could be transferred to SCID mice with adoptive transfer of purified Id-specific CD4+ T cells." (PMID 24782871, 2014). "However, the ineffectiveness of treatment towards CD4+CD25- Tregs in cancer therapy indicates that there may be other mechanisms responsible for the ability of tumor cells to evade immunological attack." (PMID 24984576, 2014). "In addition, iNKT cells exert anti-tumor functions by rapid and robust secretion of cytokines that improve DC ability to cross-prime anti-tumor T cells and enhance recruitment of other effectors such as NK cells, CD4+ T helper-1 (Th1) and CD8+ cytotoxic T (CTL) cells." (PMID 25349699, 2014). "Therefore, the profound T cell dysfunction, progressive depletion of CD4+ T cells, B cell hyper-activation, together with the increased immuno-regulatory mechanisms all collude to actively impede tumor immune-surveillance and create a permissive environment for cancer initiation and progression." (PMID 24639678, 2014).
tumor (continued). "A dominance of CD8+ T cells over CD4+ T cells (D) was associated with high numbers of FoxP3+ (CD4+) T cells (F) while low numbers of CD8+ T cells (B) were neither associated with high numbers of HLA-DR+ macrophages (K1) nor with their tumor-related localization (K3)." (PMID 24797069, 2014). "In addition to PADRE-specific CD4+ T cells being able to kill MDSCs in the tumor microenvironment, any other activated T cells could also theoretically kill MDSCs." (PMID 25531529, 2014). "Furthermore, during actual adenoviral injection in the tumor, infected tumor cells could also present TAAs to other types of immune cells, such as CD4+ T helper cells, to regulate the immunity toward an adaptive anti-tumor one." (PMID 24827739, 2014). "The efficient recognition of LCL by virion antigen-specific T cells and the correlation of target cell recognition and prolongation of mouse survival implied that increasing virion antigen-specific CD4+ T cells in T-cell preparations might increase their tumor-protective potential." (PMID 24853673, 2014). "Tumors may contain proinflammatory IL-6 that contributes to angiogenesis and cancer cachexia, as well as transforming growth factor beta (TGF-β), a product of regulatory CD4+ T cells (Tregs) which suppress effector immune cell function and contribute to tumor escape from host immune surveillance." (PMID 24955376, 2014). "It is also possible that CD4+ T cells could themselves directly kill tumor cells, e.g., through FasL/Fas interactions, similar to what has been described for killing of MHC IIPOS B lymphoma cells, or a perforin/granzyme B-dependent mechanism as described for killing of the MHC IIPOS B16 cells." (PMID 24782871, 2014). "The exaggerated TPA response in EPI−/− mice resulted in increased numbers of CD4+ T cells, neutrophils, mast cells, and eosinophils, and many of these leukocyte populations have been shown to be able to exert tumour protective effects, which could potentially bypass the function of γδ T cells." (PMID 24843010, 2014). "The impairment may be mediated by the following mechanisms: immunosuppressing factors released by tumor cells, deficient tumor antigen presentation by dendritic cells, reduced production of costimulating cytokines by helper CD4+ T-cells, and recruitment of regulatory immune cells by tumor cells." (PMID 24397835, 2014). "Interestingly, IL-21 appears to promote CD4+ T cells along Th1 differentiation and may enhance their anti-tumor effects." (PMID 25505736, 2014). "Furthermore, the CD8+ TIL586 cells recovered from different organs and tumor tissues previously transferred into 586mel-bearing mice also had potent suppressive activity and significantly inhibited the proliferation of responding CD4+ T cells." (PMID 25231413, 2014). "Moreover, DCs might be fully matured by simultaneous CD40L signals, resulting in the induction of cytotoxic CD8a+ and helper CD4+ T cells and their infiltration into tumor tissues." (PMID 25013909, 2014). "Since it is clear that nearly all CD4 effector T cell subsets can potentially produce IL-10, it is conceivable that endogenous IL-10 (such as IL-10 derived from CD4 helper/effector T cells infiltrating sites of tumor growth) may exhibits both antitumor and pro-tumor activities." (PMID 23533029, 2013). "The differential phenotypic features of Tim-3-expressing cells in blood, NILs and TILs suggest that upregulation of Tim-3 on CD4 T cells may occur in the tumor environment, and in turn, the regulatory properties of these cells may contribute to the immunosuppressive environment in tumors." (PMID 23526963, 2013). "However, a clear uptake of cytosol by CD4+ T cells after co-culture with all tumor cell lines could be observed." (PMID 24205259, 2013). "Therefore, it’s possible that Tim-3+ Foxp3+ CD4 T cells in tumor tissue might represent the highly activated Tregs that possess potent inhibitory activity." (PMID 23526963, 2013).